HDGF (heparin binding growth factor)
Diseases named in the same sentence as HDGF in open-access papers (continued):
Sharing a sentence is not in itself a finding about the gene and the disease.
gastric cancer (continued). "In gastric cancer, METTL3 promoted the m6A modification of HDGF mRNA, and the m6A reader IGF2BP3 directly recognized and bound to the m6A site on HDGF mRNA and enhanced HDGF mRNA stability." (PMID 35144642, 2022). "Notably, HDGF has been shown to facilitate cell metastasis in lung cancer, Ewing sarcoma, HCC, and gastric cancer through activating EMT signaling or promoting actin cytoskeleton remodeling and cell-matrix adhesion." (PMID 34782720, 2022). "Several studies have reported that progression of GC is promoted by m6A writers, for example, METTL3-mediated m6A modification of some mRNA (HDGF, SPHK2, and MYC), which ultimately promotes gastric cancer progression, thus, exhibiting a prognostic significance." (PMID 35778697, 2022). "The increased HDGF then activates GLUT4 and ENO2 to induce glycolysis in gastric cancer cells." (PMID 33372610, 2020). "In the present study, we found that HDGF significantly recruits HBMMSCs and stimulates the differentiation of HBMMSCs toward CAF-myofibroblasts, which further contributes to the progression of gastric cancer." (PMID 30513684, 2018). "In addition, IGF2BP3 and METTL3 improve the expression of transcription factor HDGF by directly recognizing and binding the m6A-modified HDGF, which transcriptionally accelerates the expression of GLUT4 and ENO2 to facilitate glycolysis in gastric cancer." (PMID 37280679, 2023). "However, this was not consistent with our data using the recombinant HDGF and TNFα in human gastric cancer 3-D-organoid system." (PMID 37047540, 2023). "The secreted HDGF induced tumor angiogenesis, while nuclear HDGF activated glucose transporter type 4 (GLUT4) and enolase-2 (ENO2) expression, followed by an elevation in glycolysis in gastric cancer cells, which was correlated with subsequent tumor growth and liver metastasis." (PMID 34774047, 2021). "In addition, upregulation of METTL3 in gastric cancer promotes tumor angiogenesis and glycolysis by promoting IGF2BP3-dependent hepatoma-derived growth factor (HDGF) mRNA stability, which is essential for increasing in glycolysis by activating GLUT4 and ENO2 in gastric cancer cells." (PMID 34616742, 2021). "In gastric cancer, it can be found that m6A level is at a high level for the reason that METTL3 is activated by p300-mediated H3K27, which then leads to the enhancement of the stability of hepatocellular growth factor (HDGF) mRNA by m6A modification identified by “reader” IGF2BP3." (PMID 33552994, 2020).
hepatocellular carcinoma (54 papers, 2006 to 2025). A malignant tumor that arises from hepatocytes. "Our findings provide a fundamental mechanism underlying the regulatory effect of HDGF on mitochondrial energy metabolism in hepatocellular carcinoma." (PMID 37827291, 2023). "On the other hand, HDGF expression is associated with various malignant cancers, including hepatocellular carcinoma (HCC), gastric cancer, non-small cell lung cancer, pancreatic cancer, and melanoma, to name a few." (PMID 34227049, 2022). "HDGF (Heparin Binding Growth Factor) encodes a member of the hepatoma-derived growth factor family that may be involved in proliferation and differentiation of the cell." (PMID 32528411, 2020). "Hepatoma-derived growth factor (HDGF) is a heparin-binding protein first isolated from the hepatoma cell line Hu-7 conditioned medium base on its ability to stimulate Swiss 3T3 cell proliferation." (PMID 39041204, 2024). "For example, Methyltransferase METTL3 directly mediates the m6A modification of LNCC00958 to enhance its stability, and then promotes the progression of hepatocellular carcinoma by up-regulating the expression of HDGF." (PMID 38180752, 2024). "Hepatoma-derived growth factor (HDGF) is a mitogen originally purified from the conditioned medium of Huh-7 hepatoma cells." (PMID 37827291, 2023). "HDGF is an acidic heparin-binding growth factor that was first discovered in the conditioned media of a human hepatoma cell line, Huh-745." (PMID 37479885, 2023). "Flow cytometry and the mitochondria-specific MitoSOX Red dye showed that HDGF treatment significantly increased the fluorescence intensity of MitoSOX Red in hepatoma cells in a dose-dependent manner." (PMID 37827291, 2023). "Consistently, these HDGF-depleted hepatoma cells had significantly higher invasiveness and ROS levels, as shown by DCFH-DA staining and FACS assay." (PMID 37827291, 2023). "Hepatoma-derived growth factor (HDGF) is a heparin-binding growth factor that was first identified from the conditioned medium of the Huh-7 hepatoma cell line, indicating that it can be secreted." (PMID 37301856, 2023). "Genetic silencing of superoxide dismutase 2 augmented the HDGF-induced ROS generation and oncogenic behaviors of hepatoma cells." (PMID 37827291, 2023). "Seahorse metabolic flux assays showed that NCL neutralization significantly abolished the HDGF-induced increase in basal respiration, coupled respiration, and maximal oxygen consumption in hepatoma cells." (PMID 37827291, 2023). "Next, flow cytometry using DCFH-DA staining showed that the recombinant HDGF (rHDGF) protein dose dependently increased the intracellular ROS level by up to 2-fold in hepatoma cells." (PMID 37827291, 2023). "To validate the role of ROS generation in HDGF-induced hepatocarcinogenesis, we evaluated the influence of the antioxidant N-acetyl cysteine (NAC) on HDGF-stimulated oncogenic behaviors in hepatoma cells." (PMID 37827291, 2023). "Antibody neutralization of NCL effectively abolished the HDGF-induced increase in hydrogen peroxide levels in hepatoma cells." (PMID 37827291, 2023). "Here, we first analyzed the profile of HDGF expression and ROS production in newly generated orthotopic hepatomas by ultrasound-guided implantation." (PMID 37827291, 2023). "We used adenoviral gene delivery to modulate cellular HDGF levels, and HDGF overexpression prominently augmented MitoSOX Red staining in hepatoma cells." (PMID 37827291, 2023). "Here, we generated two stable clones including shNCL#1 and shNCL#2 for analyzing the effects of NCL knockdown on HDGF-induced bioenergetics in SK-Hep-1 hepatoma cells." (PMID 37827291, 2023). "Given that hepatocyte ABs used in this study were generated from RLW cells, which is the hepatoma cell line, for translational interpretation, we needed to confirm the presence of HDGF in primary human hepatocytes (PHH)." (PMID 36982417, 2023).
hepatocellular carcinoma (continued). "ROS-detecting fluorescent dyes and flow cytometry revealed that recombinant HDGF (rHDGF) stimulated the production of superoxide anion, hydrogen peroxide, and mitochondrial ROS generation in cultured hepatoma cells in a dose-dependent manner." (PMID 37827291, 2023). "Proliferation assays showed that NAC dramatically attenuated HDGF-stimulated proliferation in hepatoma cells." (PMID 37827291, 2023). "In situ superoxide detection showed that HDGF-overexpressing hepatomas had significantly elevated ROS levels compared with adjacent nontumor tissues." (PMID 37827291, 2023). "Subsequently, we examined the relationship between HDGF and ROS generation using the Novikoff hepatoma model induced by ultrasound-guided implantation." (PMID 37827291, 2023). "HDGF, isolated from the conditioned medium of cultures of human hepatocellular carcinoma cell line Huh-7, is an acidic heparin-binding growth factor." (PMID 35053302, 2022). "Hepatoma-derived growth factor (HDGF) is a 240 amino-acid protein isolated from human hepatoma cells." (PMID 34227049, 2022). "Another study investigated the regulation of hepatoma-derived growth factor (HDGF) by K2 in hepatocellular carcinoma cells." (PMID 36296903, 2022). "It has been reported that HDGF stimulates cell proliferation in fibroblasts, endothelial cells, and hepatoma cells as well as mediates inflammation." (PMID 34227049, 2022). "In this study, we comprehensively characterized miR-129-5p and its direct target gene HDGF in the context of hepatocellular carcinoma." (PMID 35578240, 2022). "HDGF was first isolated from the Huh-7 hepatoma cell line and is primarily known for its role in cancer cell proliferation." (PMID 35293825, 2022). "During cell development, HDGF stimulates cell proliferation in fibroblasts, endothelial cells, and hepatoma cells." (PMID 33727914, 2021). "It was reported that LINC00958 can competitively bind to miRNA with hepatoma-derived growth factor (HDGF) to regulate the biological functions of mRNA in hepatocellular carcinoma." (PMID 34384029, 2021). "Many studies have also documented the role of HDGF as a mitogen with extracellular proliferative effects on hepatoma cells, fibroblasts, vascular smooth muscle cells, and endothelial cells." (PMID 33727914, 2021). "Hepatoma-derived growth factor (HDGF) was identified in research seeking to find a novel growth factor for hepatoma cells." (PMID 32545762, 2020). "HDGF is strongly expressed not only in hepatoma cells, but also in pancreatic cancer cells, including a number of pancreatic ductal carcinoma cell lines (i.e., MIA PaCa-2, PANC-1, PL45 and KP-4)." (PMID 32545762, 2020). "In hepatoma cell lines, experimental studies demonstrated that the blocking of HDGF activated both extrinsic and intrinsic apoptotic pathways." (PMID 32545762, 2020). "Our experimental studies showed that anti-HDGF therapy significantly suppressed the growth of cancer cells, such as hepatoma cells and colonic cancer cells." (PMID 32545762, 2020). "As HDGF was originally identified as a growth factor for hepatoma cells, various studies have demonstrated that HDGF is associated with the progression of HCC." (PMID 32545762, 2020). "These in vitro and in vivo experimental studies strongly suggest that HDGF acts as a growth factor for hepatoma cells." (PMID 32545762, 2020). "Hepatoma-derived growth factor (HDGF) is a heparin-binding nuclear growth factor purified from the conditioned media of Huh-7 hepatoma cells." (PMID 31711427, 2019). "HDGF has been reported to stimulate the proliferation and invasion of hepatocellular carcinoma cells via PI3K/AKT signaling." (PMID 31711427, 2019). "Hepatoma-derived growth factor (HDGF) is a ubiquitous growth factor originally isolated from conditioned medium of Huh-7 hepatoma cells." (PMID 29467272, 2018). "Increased expression of HDGF was reported as a poor prognostic marker in various cancers like hepatocellular carcinoma, gastric and lung cancers." (PMID 29568375, 2018).
hepatocellular carcinoma (continued). "Hepatoma-derived growth factor (HDGF), an acidic heparin-binding growth factor, was originally purified from the conditioned medium of a human hepatoma cell line, Huh-7." (PMID 29300772, 2018). "hepatoma‐derived growth factor (HDGF) is a heparin‐binding acidic glycoprotein that was originally identified from conditioned serum‐free medium by a human hepatoma‐derived cell line HuH‐7 and exhibits mitogenic activity in various cell types." (PMID 30004626, 2018). "HDGF was originally isolated from the conditioned medium of hepatoma-derived cells as a heparin-binding growth factor, and its role in the development of cardiovascular tissues was proved afterwards." (PMID 29358952, 2017). "With two bipartite nuclear localization sequences, HDGF is mainly localized in nucleus and stimulates the proliferation in various types of cells including fibroblasts, endothelial cells and hepatoma cells." (PMID 25938538, 2015). "It was found that exogenous HDGF supply was co-localized with NCL in cytoplasm/plasma membrane of hepatoma cells." (PMID 25938538, 2015). "HDGF is expressed in several hepatoma cell lines, including Huh-7, HepG2, PLC/PLF/5, SK-Hep1 and Mahlavu." (PMID 26101867, 2015). "Hepatoma-derived growth factor (HDGF) is a heparin-binding protein that was originally purified from the conditioned media of human hepatocellular carcinoma cell line HuH-7, which proliferate autonomously in serum-free chemically defined medium." (PMID 26296979, 2015). "By using immunofluorescence analysis, it was shown that application of anti-NCL neutralizing antibodies prominently reduced intake of HDGF in hepatoma cells." (PMID 25938538, 2015). "Our study has further demonstrated the anti-tumor efficacy of NCL inactivation via knockdown and antibodies neutralization in suppressing the tumorigenicity of hepatoma cells even in the presence of excessive HDGF." (PMID 25938538, 2015). "In a xenograft model using nude mice, HDGF-overexpressing HepG2 hepatoma cells develop larger tumors when compared to the tumors of the control counterparts." (PMID 26101867, 2015). "Immunoblot analysis showed that NCL overexpression significantly increased the HDGF protein level and stimulated the Akt phosphorylation in hepatoma cells." (PMID 25938538, 2015). "Regarding hepatoma cells, blocking HDGF activates both the Fas-mediated extrinsic and Bad-mediated intrinsic apoptotic pathways, and HDGF is therefore considered to function as a survival factor by exerting multiple anti-apoptotic effects." (PMID 26101867, 2015). "Hepatoma-derived growth factor (HDGF) is a protein of 240 amino-acid isolated from the cultured supernatants of human hepatoma cells." (PMID 25938538, 2015). "We previously showed that the reduction of the HDGF expression significantly suppresses the growth of hepatoma cells in vitro." (PMID 26101867, 2015). "It was observed that DiI staining was co-localized with more than 80% of 6xHis-tagged HDGF immunostaining at surface of hepatoma cells." (PMID 25938538, 2015). "Although HDGF was isolated from a hepatoma cell line, previous studies have shown that it plays important roles in the development and tissue repair of numerous normal organs, including the liver, kidneys, lungs and gut." (PMID 26101867, 2015). "HDGF stimulates the proliferation of hepatoma cells in vitro, and the HDGF expression is significantly higher in human HCC tissues than in adjacent non-cancerous liver tissues." (PMID 26101867, 2015). "HDGF has a mitogenic function in various cells, such as human hepatocellular carcinoma cells, fibroblasts, endothelial cells, vascular smooth muscle cells and fetal hepatocytes." (PMID 25421244, 2014). "HDGF is a secreted growth factor that has been purified from the conditioned medium of human hepatoma and is an acidic polypeptide with heparin-binding growth stimulating activity for fibroblasts." (PMID 25421244, 2014).
hepatocellular carcinoma (continued). "Hepatoma-derived growth factor (HDGF) is a novel growth factor identified from human hepatoma cell line." (PMID 23536873, 2013). "Hepatoma-derived growth factor (HDGF) is an acidic heparin-binding protein originally isolated from the conditional medium of human hepatoma cells." (PMID 23536873, 2013). "Up to now HDGF has been reported to be overexpressed in non-small cellular lung cancer, hepatocellular carcinoma, colorectal carcinoma, oesophagal carcinoma, pancreatic carcinoma and melanoma." (PMID 22014102, 2011). "HDGF was shown to be overexpressed in several types of tumors, like e.g. hepatocellular carcinoma or melanoma." (PMID 22014102, 2011). "Hepatoma-derived growth factor (HDGF) is a heparin-binding protein originally isolated from the conditioned medium of HuH-7 hepatoma cell line." (PMID 20846397, 2010). "HDGF was first cloned from the conditioned medium of hepatoma cell line HuH-7 and was found to be an acidic, heat-labile heparin-binding protein with mitogenic activity for fibroblasts." (PMID 20846397, 2010). "Of the six members of the Hepatoma-derived growth factor family only HDGF, HRP-2 and HRP-3 are expressed in the central nervous system." (PMID 16430771, 2006). "So far, most studies addressed HDGF which was initially purified from the supernatant of human hepatoma cell lines." (PMID 16430771, 2006). "Furthermore, high HDGF expression correlates with poor prognosis in patients with hepatocellular carcinoma, pancreatic cancer, cholangiocarcinoma, gallbladder adenocarcinoma, and esophageal cancer." (PMID 41278276, 2025). "Furthermore, LINC00958 can uptake miR3619-5p to increase HDGF expression, which promotes adipogenesis and the progression of hepatocellular carcinoma (HCC)." (PMID 38125749, 2023). "Since it has been reported that surface NCL transmits the oncogenic signaling of HDGF, we evaluated whether blocking NCL signaling affected HDGF-induced ROS generation in hepatoma cells." (PMID 37827291, 2023). "Interestingly, application of an anti-NCL antibody not only attenuated the basal ECAR but also completely abrogated the HDGF-stimulated ECAR in hepatoma cells." (PMID 37827291, 2023). "Finally, we used the specific mitochondria-targeted antioxidant MitoQ to disrupt the stimulatory effect of HDGF on the invasiveness of hepatoma cells." (PMID 37827291, 2023). "In addition, NCL neutralization abrogated HDGF-induced mitochondrial ROS production in hepatoma cells." (PMID 37827291, 2023). "Hence, we elucidated the influence of HDGF on the expression of these ROS-clearing enzymes in hepatoma." (PMID 37827291, 2023). "Thus far, only one receptor, nucleolin (NCL), has been identified to interact with and mediate the uptake of HDGF in hepatoma cells." (PMID 35293825, 2022). "Interestingly, high expression of HDGF is observed in a variety of cancers, such gliomas, bladder and ovarian cancers as well as hepatocellular carcinomas." (PMID 35293825, 2022). "Furthermore, many studies indicate that HDGF is a mitogen with extracellular proliferative effects on hepatoma cells, fibroblasts, vascular smooth muscle cells, and endothelial cells." (PMID 34227049, 2022). "Our study establishes a link between hepatoma-derived growth factor HDGF and miR-129-5p." (PMID 35578240, 2022). "A time-course study indicated that TNF-α acts as a priming factor to increase HDGF release from hepatoma cells during H. p. infection, and HDGF is also known as an intermediator that amplifies and maintains downstream COX-2/TNF-α signaling through the activation of nuclear factor kappa B (NF-κB)." (PMID 35053302, 2022). "Hepatoma derived growth factor (HDGF) is produced by neurons." (PMID 35293825, 2022). "HDGF was primarily obtained from the conditioned media of Huh-7 hepatoma cells." (PMID 34368121, 2021). "HDGF was originally obtained from the conditioned media of HuH-7 hepatoma cells." (PMID 34774047, 2021).